TNFRSF4 (TNF receptor superfamily member 4)
Diseases named in the same sentence as TNFRSF4 in open-access papers (continued):
Sharing a sentence is not in itself a finding about the gene and the disease.
chronic myeloid leukemia (5 papers, 2013 to 2024). "In the bone marrow of newly diagnosed chronic myeloid leukemia patients, TNFRSF4 mRNA levels were dramatically raised and linked with the expression of the Treg-restricted transcription factor FOXP3." (PMID 36100891, 2022). "For example, regulatory T cells expressing Tnfrsf4 facilitate the immune evasion of stem cells in chronic myeloid leukemia." (PMID 39742265, 2024). "Consistently, it has been reported that Treg cells with the expression of TNFRSF4 were more immunosuppressive and facilitated tumor immune evasion, and promote tumor development in nasopharyngeal carcinoma, cutaneous squamous cell carcinoma and chronic myeloid leukemia." (PMID 35831283, 2022).
leukemia (5 papers, 2019 to 2025). A malignant (clonal) hematologic disorder, involving hematopoietic stem cells and characterized by the presence of primitive or atypical myeloid or lymphoid cells in the bone marrow and the blood. "Mechanistically, Tnfrsf4 antibody treatment significantly increased the CD8/Treg ratio in BM without depleting/reducing Treg numbers, which resulted in reduced leukemia and reduced numbers of BM LSCs." (PMID 34727093, 2021).
liver cancer (5 papers, 2022). An epithelial or non-epithelial malignant neoplasm that arises from the liver. "In another case, the transcript ENST00000379236.3 (from the TNFRSF4 gene) expressed much higher in liver cancer over normal liver tissue, but also showed considerable expression level in other cancer and tissue types." (PMID 35473935, 2022). "TNFRSF4 may be a promising immunotherapy target and prognostic biomarker for liver cancer." (PMID 35958614, 2022).
mesothelioma (5 papers, 2020 to 2023). A usually malignant and aggressive neoplasm of the mesothelium which is often associated with exposure to asbestos. "OX40 (TNFRSF4) and OX40L (TNFSF4) have been implicated in mesothelioma." (PMID 33952230, 2021).
Kaposi's sarcoma (4 papers, 2017 to 2026). A malignant neoplasm characterized by a vascular proliferation which usually contains blunt endothelial cells. "The mutation of TNFRSF4, encoding OX40, led to the deficiency of T cells, thus inducing Kaposi sarcoma, an endothelial malignancy." (PMID 34900670, 2021).
metastatic carcinoma (4 papers, 2021 to 2023). A carcinoma which has spread from the original site of growth to another anatomic site. "A phase I clinical research also supported that Ivuxolimab (a TNFRSF4 agonist) showed well tolerance and effective anti-tumor capacity in locally advanced or metastatic cancers, including HCC." (PMID 35193632, 2022). "Several OX40 (TNFRSF4) targeting molecules, such as ivuxolimab, vonlerolizumab and tavolimab, show in clinical trials preliminary anti-cancer action in locally advanced or metastatic cancers." (PMID 36224560, 2022).
endometrial carcinoma (3 papers, 2022 to 2024). A malignant tumor arising from the epithelium that lines the cavity of the uterine body. "As a secondary immune checkpoint, TNFRSF4 has potential implications for endometrial cancer patients’ prognosis and immunomodulation." (PMID 38590525, 2024).
squamous carcinoma (3 papers, 2021 to 2024). "DDR-deficient types had lower expressions of STING1 (p = 0.01), CD28 (p = 0.020), HLA-DRB6 (p = 0.014) in adenocarcinoma, lower TNFRSF4 (p = 0.017), and TGFB1 expressions (p = 0.033) in squamous carcinoma, and higher CD40 (p = 0.012) and TNFRSF14 expressions (p = 0.022) in SCLC." (PMID 34604048, 2021).
endometriosis (2 papers, 2024 to 2025). The growth of functional endometrial tissue in anatomic sites outside the uterine body. "In addition, we explored the immune checkpoints (PDCD1, PDCD1LG2, CTLA4, TNFRSF9, and TNFRSF4) expression levels between the endometrium and endometriosis." (PMID 40165344, 2025).
myelodysplastic syndrome (2 papers, 2020 to 2021). A clonal hematopoietic disorder characterized by dysplasia and ineffective hematopoiesis in one or more of the hematopoietic cell lines. "In addition, based on our clinical center data, we validated TNFRSF4 expression level of non-M3 AML patients was significantly higher than that of HDs and Myelodysplastic syndrome (MDS) Excess blasts (EB)-1,2 patients." (PMID 32390761, 2020).
nematode infection (2 papers, 2014 to 2022). "Indeed the inhibition of the TNFRSF4 cytokine is known to induce a more efficient expulsion of helminths in mice models of nematode infection." (PMID 24939584, 2014).
pancreatic adenocarcinoma (2 papers, 2022). "We found that HAVCR1 was associated with HHLA2, CD44 and TNFRSF4 in Liver hepatocellular carcinoma and Pancreatic adenocarcinoma." (PMID 35754803, 2022). "Furthermore, HAVCR1 expression was correlated with other immune molecules such as HHLA2 (Human endogenous retrovirus-H long terminal repeat-associating protein 2), CD44 and TNFRSF4 (TNF Receptor Superfamily Member 4) in Liver hepatocellular carcinoma and Pancreatic adenocarcinoma." (PMID 35754803, 2022). "“Profile-B” is made by the 6 molecules differently expressed in Pancreatic adenocarcinoma (PAAD) patients (i.e., TIM3 (HAVCR2), OX40 (TNFRSF4), GITR (TNFRRSF18), TIGIT, LAG3 and CTLA4)." (PMID 36224560, 2022).
aneurysm (1 paper, 2020). Bulging or ballooning in an area of an artery secondary to arterial wall weakening. "TNFRSF4 (increased in our study) is a member of the TNF-receptor superfamily that is involved in NF-κB pathway activation and has also been found to be increased in aneurysm tissue." (PMID 33156839, 2020).
keloid (1 paper, 2020). An irregularly shaped, elevated mark on the skin caused by deposits of excessive amounts of collagen during wound healing. "Our results associate keloid tissues with an inflammatory milieu representing multiple T-helper pathways, including the Th2 (e.g. IL-4R, CCL11, TSLP, TNFSF4/OX40L, TNFRSF4/OX40), Th1 (e.g. IFNγ, CXCL10/11), Th17/Th22 (e.g. PI3, CCL20, S100As) axes, as well as the JAK/STAT signaling molecule JAK3." (PMID 33329590, 2020).
kidney stone (1 paper, 2025). "Concurrently, six protein ratio pairs were found to inhibit kidney stone occurrence: GGT1/MME protein level ratio, ACE2/MME protein level ratio, ITIH3/VCAM1 protein level ratio, GZMA/TNFRSF8 protein level ratio, CRADD/HSPA1A protein level ratio and GZMA/TNFRSF4 protein level ratio." (PMID 40673688, 2025).
mucinous ovarian cancer (1 paper, 2013). An invasive malignant neoplasm that arises from the ovary and is characterized by the presence of malignant epithelial cells that contain intracytoplasmic mucin and may resemble the epithelial cells of the endocervix or gastrointestinal tract. "One other SNP rs3753348 showed association with a more than three-fold risk with survival in mucinous ovarian cancer; this SNP resides in the 5 kb region between tumor necrosis factor receptor superfamily members 4 and 18 (TNFRSF4 and TNFRSF18) on chromosome 1." (PMID 23382860, 2013). "We report an association between risk of death due to mucinous ovarian cancer and a SNP in a gene cluster containing TNFRSF18 and TNFRSF4." (PMID 23382860, 2013).
primary immunodeficiency (1 paper, 2021). "In particular, we detected that ZAP70 was enriched in primary immunodeficiency, TNFRSF4, and CXCL5 were enriched in cytokine-cytokine receptor interaction, CTSG was enriched in the renin-angiotensin system, and the CHRM2 and CTSG were enriched in neuroactive ligand-receptor interaction." (PMID 34133324, 2021).
tumor (600 papers, 2009 to 2026). "CD276, HLA-A, and TNFRSF4 are immune checkpoint proteins that are associated with tumor immune evasion." (PMID 39771050, 2024). "The agonist anti-TNFRSF4 antibody is used to inhibit metastasis of metastatic cutaneous squamous cell carcinoma (mSCC) by significantly inhibiting Tregs and by improving the infiltration of tumor-associated CD4+ T cells." (PMID 34367975, 2021). "Thus, the diminished activated TNFRSF4+ Tregs in tumor lesions are associated with the positive clinical outcome and could be used as potential predictors and therapeutic targets for neoadjuvant chemoimmunotherapy." (PMID 35831283, 2022). "In the tumor microenvironment, TNFRSF4 (OX40)+ Tregs exhibit enhanced immunosuppressive activity and correlate with poor prognosis across multiple cancers." (PMID 41208977, 2025). "Compared to Treg.1, Treg. showed significantly up-regulated genes (TNFRSF4/OX40, TNFRSF18/GITR, TNFRSF9/4–1BB, TNFRSF1B/TNFR2 and LAIR2) associated with suppressive functions of tumor-infiltrating Tregs49." (PMID 39803458, 2025). "Preclinical results have demonstrated that agonistic antibodies targeting 4-1BB (TNFRSF9) and OX40 (TNFRSF4) can elicit long-term anti-tumor immunity in humanized mouse models." (PMID 39979981, 2025). "Given its significance in prediction and therapy, clinical agents aimed at TNFRSF4 present a promising avenue for managing tumor progression." (PMID 38590525, 2024). "This preclinical model led to the identification of significant dysregulation of TNFRSF4 in cisplatin-resistant tumours." (PMID 38809883, 2024). "A series of research studies have explored the role of TNFRSF4 as a therapeutic agent in preclinical tumor models, highlighting its significant contribution to immunotherapy." (PMID 38590525, 2024). "TNFRSF4 can be used as a potential target to reduce the function of Treg and improve the anti-tumor immunity to NSCLC." (PMID 37671151, 2023). "Compared with normal tissues, only SLURP1 was downregulated in tumor tissues, while the expression levels of DKK1, GAST, IGHM, IL12RB2, STC2, and TNFRSF4 were upregulated in tumor tissues." (PMID 39282247, 2023). "Meanwhile, another study found that ivolizumab (TNFRSF4 agonist) is expected to be a new oncologic agent due to its well-tolerated and effective anti-tumor capacity in locally advanced or metastatic HCC." (PMID 37006257, 2023). "Anti-TNFRSF4 antibody augmented antitumor immunity in animal models with several types of cancers, and the anti-tumor effects were mainly dependent on the reduction of Treg cells in tumors." (PMID 35831283, 2022). "Our result showed that TNFRSF4 was overexpressed in cancer tissues compared with adjacent normal tissues, and it was mainly located in the TILs within the tumor stroma." (PMID 35562682, 2022). "Lastly, our study identified TNFRSF4 as a potential target to reduce the function of Tregs and improve anti-tumor immunity against NSCLC." (PMID 35831283, 2022). "Multiple studies have demonstrated that TNFRSF4 can work as a therapeutic agent and play a significant role in immunotherapy of preclinical tumor models." (PMID 33816550, 2021). "Inhibitory immune marker (HAVCR2) and activating immune receptors (CD80, TNFRSF4, and TNFRSF9) were both at higher levels in the high-risk group, suggesting a complex immune microenvironment within the tumor." (PMID 33850474, 2021). "Other genes identified in this study as over-expressed in CIN3/AIS lesions compared to normal cervical tissue are also associated with tumor development (KRT7, TNFRSF18 and TNFRSF4)." (PMID 35008799, 2021). "TNFRSF4 agonists are currently being investigated alone or in combination with other immunotherapies for the treatment of various tumor entities." (PMID 34727093, 2021). "Growth factor-related genes are also associated with tumor metastasis, among which LTα, TNFRSF12α, TNFRSF25, TNFRSF4, and IRF9 can mediate HNSCC tumorigenesis and metastasis through the NF-κB signaling pathway." (PMID 33330624, 2020).
tumor (continued). "In various tumor models, anti-TNFRSF4 has been shown to enhance CD8+ T cells infiltration and reduce Treg cells infiltration into the tumor." (PMID 32390761, 2020). "Another research also found a dependence on direct TNFRSF4 ligation on CD8+ T cells to increase tumor specific cytotoxicity in vivo." (PMID 32390761, 2020). "Series researches have investigated that TNFRSF4 as a therapeutic agent plays a significant role in immunotherapy of preclinical tumor models." (PMID 32390761, 2020). "Additionally, higher levels of Treg cells were found in the primary tumor tissue, expressing elevated levels of costimulatory genes associated with immune checkpoints (CD27, ICOS, TNFRSF4, and TNFRSF18) and exhaustion markers (CTLA4 and TIGIT)." (PMID 40303346, 2025). "Both DCs and TAMs from the tumor exhibit some expression of TNFSF4, encoding OX40 Ligand (OX40L), suggesting the increased frequency of TNFRSF4 activation could be due to interactions with these cell types." (PMID 39811671, 2025). "Furthermore, tumor cytotoxicity can be augmented by upregulating TNFRSF4 within chimeric antigen receptor T cells via transfection and synergism with ICI." (PMID 38590525, 2024). "Notably, genes of tumor necrosis factor receptor superfamily TNFRSF9, TNFRSF18, and TNFRSF4 were highly and exclusively expressed in the Tregs infiltrating the tumor." (PMID 36750562, 2023). "Ligation of OX40 (TNFRSF4, CD134) on the effector T cell surface by OX40 agonists causes the receptor to oligomerize (cluster) and stimulates intracellular signaling, which enhances anti-tumor immunity leading to therapeutic effects in cancers." (PMID 38140230, 2023). "In addition, TNFRSF4 is one of the most highly expressed genes in tumor-invasive Tregs compared to those in healthy tissues." (PMID 35626661, 2022). "Both high and low expressions of TNFRSF4 have been reported in tumor tissues." (PMID 35945754, 2022). "In addition, TNFRSF4-positive T cells can reduce inhibitory factors in the tumor immune microenvironment and effectively inhibit tumor invasion and metastasis." (PMID 35754803, 2022). "Trajectory analyses also revealed exhausted CD8+ T cells and immune-suppressive TNFRSF4+ Treg cells in tumours that might have been derived from peripheral CX3CR1+CD8+ T and naïve Treg cells, respectively." (PMID 34956172, 2021). "TNFRSF4 mainly acts by enhancing the capacity of T cells, which can inhibit tumor metastasis by significantly stimulating adaptive immunity and triggering a positive change in the immune tumor microenvironment." (PMID 34367975, 2021). "Trajectory analyses reveal exhausted CD8+ T and immune-suppressive TNFRSF4+ Treg cells in tumours might derive from peripheral CX3CR1+CD8+ T and naïve Treg cells, respectively." (PMID 33531485, 2021). "With the success of immune checkpoint blockade therapies and promise of programmed death pathway-targeted agents, TNFRSF4 could represent a potential target for future therapeutics to control tumor progression in HNSCC." (PMID 33799782, 2021). "We analyzed the downregulation of co-stimulatory molecules such as TNFRSF and TNFRSF4 in the C2 subtype, which may weaken T-cell activation and immune effects in the tumor microenvironment, thereby partially explaining why the immune efficacy remains poor despite high PD-L1 expression." (PMID 41041304, 2025). "Many downregulated genes in tumour‐infiltrating peripheral CD8+ T cells are associated with classical IFN responses (IFI6, IFI27, MX1, STAT1, EPSTI1 PARP9, ISG15), cell proliferation (STMN1, CENPF, HELLS, NUSAP1, and DNPH1), and T cell costimulation (CD28, TMIGD2, TNFRSF4, CD27, and TNFRSF18)." (PMID 39350478, 2024). "In addition, TNFRSF4 can potentially be used as a molecular target to reduce the function of Treg and improve the anti-tumor immunity against NSCLC, which help us better understand the mechanism of cell synergy in the clinical response to neoadjuvant immunotherapy." (PMID 37671151, 2023).
tumor (continued). "In short, TNFRSF4 might act as a win-win path to reestablish T-cell anti-tumor activity." (PMID 35562682, 2022). "While the top three KLF4-assocaited genes correlated with a tumor stimulatory effect for several tumors were CX3CL1, TNFRSF4, and IL1A." (PMID 40299916, 2025). "Herein, several KLF4-assocaited genes, C10orf54 and CD274 were correlated with tumor suppression, while others, including CX3CL1, TNFRSF4, and IL1A, were correlated with tumor stimulation." (PMID 40299916, 2025). "Comparative analysis revealed tumor-specific upregulation of GLRX3, IL1RN, and TNFRSF4 (p < 0.001), contrasting with downregulation of FCGRT, UBN2, and WNT5B in EC versus normal tissues." (PMID 40722666, 2025). "Key immune checkpoints B7-H3 (CD276), OX40 (TNFRSF4) and TIM3 (HAVCR2) also displayed significantly higher expression (p < 0.05) in some tumor slides." (PMID 39529126, 2024). "Costimulatory molecules ICOS, TNFRSF4, and TNFRSF18 are expressed on the surface of tumor-infiltrated Tregs and favor suppressive function of Tregs." (PMID 38358826, 2024). "IDO1 is positively correlated with CD274, TNFRSF9, TNFRSF4, PDCD1LG2, IDO2, and CD48 in many tumor types." (PMID 38539263, 2024). "Both HCC- and CCA-derived tumour infiltrating Tregs express high levels of co-stimulatory IgSF (ICOS) and TNFRSF (4-1BB, OX40, GITR) members." (PMID 38440738, 2024). "In T cells, immune stimulation by the tumor led to the up-regulation of many co-stimulatory receptors, including ICOS, TNFRSF18, TNFRSF4, and TNFRSF9/4-1BB." (PMID 39475596, 2024). "In contrast, T cells carrying a TCR found exclusively in the tumour were enriched for exhaustion markers (CTLA4) and regulatory genes (FOXP3, TNFRSF4)." (PMID 38030622, 2023). "Tregs, denoted by increased expression of Foxp3, Ctla4, and Tnfrsf4 (CD134), represented 4.5% of sensitive tumor T cells compared to half as many (2.3%) in the resistant populations." (PMID 35924165, 2022). "Alongside TNFRSF4/OX40 and TNFRSF9/4-1BB, we selected a number of markers of tumor-resident Tregs (CTLA4, ICOS, TIGIT, and FOXP3) and performed k-means clustering for all UPS, MFS, and DDLS samples in the TCGA." (PMID 35558159, 2022). "Thirdly, in vitro experiments confirmed the TNFRSF4 oncogenic effect in HCC, and the mechanism as a tumor promoter needs to be explored in further research." (PMID 36148160, 2022). "TNFRSF4 (OX40) (also a classical necroptosis related gene) was members of the TNF receptor superfamily (TNFRSF), proved to have an anti-tumor and regulate the function of immune cells function." (PMID 36059470, 2022). "TNFRSF4, CD4, and CD8 mainly expressed on the tumor stroma and displayed a co-localization pattern observed in both the separate and merged images." (PMID 35562682, 2022). "While comparing with normal Tregs, tumor Tregs had increased expression of multiple genes related with immune suppression, including DUSP4, IL2RA, TNFRSF4, LAYN and LGALS1." (PMID 35664061, 2022). "The comparison of gene expressions in tumor and normal tissues revealed that CTSG and LCORL were downregulated, while TNFRSF4 and PLAU were upregulated in OSCC tissues." (PMID 34497859, 2021). "When the same analyses were done using PEA Oncology II profiling data, 10 proteins correlated to tumor stage (P < 0.05), for example, CD160, TNFRSF4/OX40L, XPNPEP2, SPARC, MAD homolog 5/SMAD5, CPE, hK8/KLK8, WIF‐1, TCL1A, and MIC‐A/B." (PMID 33768639, 2021). "Tumor necrosis factor receptor superfamily, member 4 (TNFRSF4) is a co-stimulatory molecule, and agonists of this molecule have been described to increase anti-tumor immunity through enhancing T cell response and suppressing T reg cells." (PMID 28174608, 2017). "Ligation of co-stimulatory T cell receptors, such as OX40 (Tnfrsf4, CD134), 4-1BB (Tnfrsf9, CD137) and GITR (Tnfrsf18, CD357), with agonist mAbs has been shown to augment the anti-tumor immune response in numerous cancer models." (PMID 25411639, 2014).